NOTCH4 (notch receptor 4)
Diseases named in the same sentence as NOTCH4 in open-access papers (continued):
Sharing a sentence is not in itself a finding about the gene and the disease.
epilepsy (1 paper, 2015). A brain disorder characterized by episodes of abnormally increased neuronal discharge resulting in transient episodes of sensory or motor neurological dysfunction, or psychic dysfunction. "Overall, Notch 4 had an increase in staining in the BAVM vessels and surrounding tissue when compared to control epilepsy vessels." (PMID 25846406, 2015).
esophageal squamous cell carcinoma (1 paper, 2020). Esophageal squamous cell carcinoma (ESCC) is a type of esophageal carcinoma (EC) that can affect any part of the esophagus, but is usually located in the upper or middle third. "There are few studies directly linking NOTCH signaling with ICB therapy in addition to Donghai Xiong’s finding that in one patient with esophageal squamous cell carcinoma (ESCC) who developed HPD after anti-PD-1 immunotherapy, somatic mutations of NOTCH4 were not present in the pretherapy tumor." (PMID 33479597, 2020).
fibromyalgia (1 paper, 2014). A chronic disorder of unknown etiology characterized by pain, stiffness, and tenderness in the muscles of neck, shoulders, back, hips, arms, and legs. "Fibromyalgia has been genetically linked to the HLA region (6p21.3) 63, which includes several genes associated with Notch signalling (e.g. Notch4, FKBP5, TNXB, MTCH1 and TNF-a) or with stem cell maintenance and proliferation (e.g. POU5F1, Flot1, MAPK14, Rgl2 and Rab44)." (PMID 25164209, 2014).
gastric adenocarcinoma (1 paper, 2020). "The expression of Notch1, Notch2, Notch3 and Notch4 proteins, which were examined by immunohistochemistry, were higher in the gastric adenocarcinoma tissues than that in the normal gastric tissues." (PMID 32028262, 2020).
glomerular diseases (1 paper, 2019). "Notch signaling has been relevant in several glomerular diseases, but, of the four Notch receptors, Notch4 has been the least investigated in this context." (PMID 31727625, 2019).
HIV-1 infection (1 paper, 2019). The type species of lentivirus and the etiologic agent of acquired immunodeficiency syndrome (AIDS). "Since many cells appeared to activate Notch4 upon HIV-1 infection, a global knockdown of Notch4 in the Tg26 mice was the approach taken in this study." (PMID 31727625, 2019).
infantile hemangioma (1 paper, 2016). "Interestingly, some of these genes also play roles in cell signaling pathways that have been linked to the pathogenesis of infantile hemangioma; namely, VEGFA in the VEGF/VEGFR pathway, ANGPT2 and ANGPTL1 in the Tie2/Angiopoietin signaling pathway and NOTCH3, NOTCH4 and JAG1 in the Notch pathway." (PMID 26772808, 2016).
Infertility (1 paper, 2025). "In the non-ART sample, we identified genome-wide significant fetal effects on fetal survival for SNPs within regions harboring genes relevant to infertility and fetal development, such as MDC1, MICB, HCP5, and NOTCH4." (PMID 41325449, 2025).
interstitial lung disease (1 paper, 2025). A diverse group of lung diseases that affect the lung parenchyma. "In the Saudi SCD dataset, we identified the marker rs3132946 in NOTCH4, which has been previously reported as a marker linked to interstitial lung diseases (ILD)." (PMID 41409427, 2025).
ischemia (1 paper, 2012). A hypoperfusion of the BLOOD through an organ or tissue caused by a PATHOLOGIC CONSTRICTION or obstruction of its BLOOD VESSELS, or an absence of BLOOD CIRCULATION. "EA pretreatment significantly enhanced Notch1, Notch4 and Jag1 gene transcriptions in the striatum, except Notch1 intracellular domain level, which could be increased evidently by ischemia." (PMID 22989188, 2012).
ischemic stroke (1 paper, 2020). A stroke disorder caused by obstruction of blood flow to the brain, due to thrombotic (local blood clot formation) or embolic (due to a blood clot or other material traveling from another site) event. "In addition, the NOTCH4 rs3134931 SNP was highly associated with circulating serum or plasma MPO levels, which were responsible for the incidence as well as development of the CHD and ischemic stroke." (PMID 33317561, 2020).
Lewis lung carcinoma (1 paper, 2024). "In these established tumors, 6-3-A6/E7011 inhibited further growth in B16F10 and Py8119, which expressed endothelial Notch4, but not in the Lewis lung carcinoma model." (PMID 38984877, 2024).
lung disease (1 paper, 2018). "Genes known to regulate T cell numbers and activation (Btnl family, Notch4) are among the limited list of potential causal variants leading to lung disease in this model and the bronchoalveolar lavage of protected subcongenic mice had fewer lymphocytes, post bleomycin, than did C57BL/6J mice." (PMID 30173367, 2018).
lung squamous cell carcinoma (1 paper, 2021). "At the same time, in lung squamous cell carcinoma, compared with NOTCH4-WT patients (ORR = 17.9%), NOTCH4-MUT patients (ORR = 50.0%) tended to have a better response to ICI treatment." (PMID 34284787, 2021).
malaria (1 paper, 2022). Malaria is a serious and sometimes fatal disease caused by a parasite that commonly infects a certain type of mosquito which feeds on humans. "In the liver, Myh10, Tubb1, and Notch4 were constitutively expressed and their expression responded to both blood-stage malaria and vaccination." (PMID 35214745, 2022). "The constitutive expression of Myh10, approximately 51, resembled that of Notch4, but its response to malaria and vaccination was totally different from that of Notch4." (PMID 35214745, 2022).
metabolic syndrome (1 paper, 2022). A cluster of metabolic risk factors for CARDIOVASCULAR DISEASES and TYPE 2 DIABETES MELLITUS. "We identified non-synonymous mutations e.g., in ApoM, Notch4, Slc39a7, Smim29 genes and other variations in or near genes associated with metabolic syndrome in human genome-wide association studies." (PMID 36014934, 2022).
metastatic tumors (1 paper, 2021). "PDE4DIP, ROBO1, and NOTCH4 mutations were observed only in metastatic tumors, whereas mutations specific to primary tumors were undetectable." (PMID 34158601, 2021).
migraine headache (1 paper, 2019). "In addition, a migraine headache pathway of related proteins also appears in this comparison, most notably ITGB3, KCNK18, NOTCH4, and LRP1 which could be interacting with glutamate receptors." (PMID 31026304, 2019).
oral cancer (1 paper, 2019). "The purpose of the study was to determine the differential expression pattern of Notch4 between the major subtypes of oral cancer such that a reliable diagnostic marker could be established for the improved treatment of OVC patients." (PMID 29162408, 2019). "Interestingly complete downregulation of Notch4 was observed in OVC patient samples confirming the cell and disease context specific role of Notch4 within the closely related oral cancer subtypes." (PMID 29162408, 2019).
ovarian endometrioid carcinoma (1 paper, 2025). "These included alterations in RAD51C, NOTCH4, SMARCA4, SMARCA1 and JAK1 in ovarian endometrioid carcinomas and SMARCA4 genes in ovarian mucinous carcinomas." (PMID 40981433, 2025).
ovarian mucinous carcinomas (1 paper, 2025). "In addition to identifying genes previously known to be involved in these tumors, we identified alterations in RAD51C, NOTCH4, SMARCA1/4, and JAK1 in ovarian endometrioid, ESR1 in uterine endometrioid, and SMARCA4 in ovarian mucinous carcinomas." (PMID 40981433, 2025).
pancreatitis (1 paper, 2022). Inflammation of the pancreas. "To further test the hypothesis that the deletion of Notch4 may affect pancreatic tumorigenesis in the early stage, we employed a caerulein-induced pancreatitis model." (PMID 36970723, 2022). "The functional impact of Notch4 on early pancreatic tumorigenesis was further verified using a caerulein-induced pancreatitis model, in which we found that the inactivation of Notch4 ameliorated the structure integrity of the acinar cells and reduced the incidence of ADM in vivo." (PMID 36970723, 2022).
polymyalgia rheumatica (1 paper, 2016). A syndrome characterized by pain, stiffness, and tenderness of the proximal muscle groups including the shoulder, pelvic girdle and the neck. "For polymyalgia rheumatica (PMR), two SNPs in the HLA region reached genome-wide significance: rs3096702 (OR=1.5 (95% CI: 1.3–1.8), P=2.0 × 10−8) and rs6910071 (OR=1.6 (95% CI: 1.3–1.8), P=2.7 × 10−8) located upstream of Notch4 and in C6orf10, respectively." (PMID 27109359, 2016).
prostate tumor (1 paper, 2015). "Prostate was the most frequently mutated cell type for both NOTCH1 and NOTCH2 but prostate tumor cell lines did not contain any mutations in NOTCH3 or NOTCH4 (right hand side)." (PMID 25907971, 2015).
pulmonary hypertensive (1 paper, 2022). "To investigate the expression of Notch4 in normal and pulmonary hypertensive lungs, we examined lung tissues from 4 individuals with HPH undergoing lung transplantation compared with lung tissues from 4 non-PH individuals." (PMID 35016680, 2022).
pulmonary tuberculosis (1 paper, 2023). A bacterial infection that affects the lungs and is caused by Mycobacterium tuberculosis. "Taken together, these results indicated that higher Notch4 expression is associated with severer pulmonary TB." (PMID 36817473, 2023). "Genotype and Allele distribution and frequencies of Notch4 gene rs422951and rs206018 in pulmonary tuberculosis patients and controls." (PMID 36817473, 2023). "Notch4 expression was significantly increased in TB patients and associated with severer pulmonary TB." (PMID 36817473, 2023). "We found Notch4 gene rs206018 and rs422951 polymorphisms were associated with susceptibility to pulmonary tuberculosis." (PMID 36817473, 2023). "Moreover, we identified that the rs206018 C allele was associated with higher level of Notch4 in PBMCs from pulmonary TB patients." (PMID 36817473, 2023). "Furthermore, Notch4 expression increased in TB patients and higher Notch4 expression correlated with the severer pulmonary TB." (PMID 36817473, 2023).
renal dysfunction (1 paper, 2024). "NOTCH4 expression (at follow-up) was only associated with renal dysfunction in these patients." (PMID 38502427, 2024).
scrub typhus (1 paper, 2024). Scrub typhus is a rare dust mite-borne infectious disease caused by the Orientia tsutsugamushi bacterium and characterized clinically by an eruptive fever which is potentially serious. "Our finding of increased Notch ligand DLL1 in plasma and decreased expression of the receptor Notch4 whole blood in scrub typhus patients was mirrored in vitro in monocytes infected with O. tsutsugamushi." (PMID 38502427, 2024). "In contrast to DLL1, NOTCH4 was downregulated in whole blood in scrub typhus patients." (PMID 38502427, 2024). "Thus, high levels of DLL1 and low levels of NOTCH4, as seen in the present study, could potentially contribute to an inflammatory phenotype in scrub typhus patients." (PMID 38502427, 2024). "Nonetheless, this first report of Notch signaling in scrub typhus patients suggesting that an imbalance between enhanced DLL1 levels and decreased NOTCH4 expression could contribute to the pathogenesis of O. tsutsugamushi infection." (PMID 38502427, 2024).
sleep-disordered breathing (1 paper, 2022). "Several factors have been identified (e.g., sex, polymorphisms in the TASK2/KCNK5, NOTCH4 and CAT genes and pre-term birth) to predict individual vulnerabilities to hypoxia-related sleep-disordered breathing." (PMID 36582343, 2022).
Stroke (1 paper, 2023). Sudden impairment of blood flow to a part of the brain due to occlusion or rupture of an artery to the brain. "The molecular and migratory capacities of SVZ neuroblasts are altered in stroke; genes such as Hif-1α or Notch4 are upregulated, and molecules such as MMPs are overexpressed in SVZ neuroblasts in response to stroke in order to facilitate emigration." (PMID 37047560, 2023).
uterine cancer (1 paper, 2022). Primary or metastatic malignant neoplasm involving the uterine corpus and/or the cervix. "Multivariate analysis identified expression alterations of NOTCH3 and NOTCH4, as a significantly independent prognostic factor for overall survival in patients with uterine cancer." (PMID 35136410, 2022). "The data of our study for the first time demonstrate that the Notch signaling pathway receptor NOTCH4 may also play an important role in the survival of patients with uterine cancer." (PMID 35136410, 2022). "Expression alterations of NOTCH2, NOTCH3, NOTCH4, JAG2, and HES1 were evaluated as independent and significant prognostic factors for uterine cancer patients." (PMID 35136410, 2022). "NOTCH2, NOTCH3, NOTCH4, JAG2, and HES1 may be used as independent and significant prognostic factors for uterine cancer patients." (PMID 35136410, 2022).
tumor (128 papers, 2004 to 2026). "On clinical correlation, Notch3 (rs1043994) A > G is associated with advanced disease stage in CRC, while Notch1 and Notch4 showed an association with depth of invasion and tumor grade, respectively." (PMID 41027955, 2025). "NOTCH4 mutation positively correlates with infiltration of diverse immune cells (tumour-infiltrating lymphocytes), the release of immunostimulatory chemokines like CXCL10 and CXCL9, and the recruitment of CD8 T cells and dendritic cells." (PMID 41008920, 2025). "They found that NOTCH4 mutation is significantly associated with strengthened tumour immunogenicity, the expression of costimulatory molecules and activation of the antigen-processing machinery leading to a better response." (PMID 41008920, 2025). "The increased expression of NOTCH3 and NOTCH4 in tumor tissues can be linked to their role in promoting cellular proliferation and survival, common features of tumorigenesis." (PMID 39286249, 2024). "Gut microorganisms, genetic mutations like POLE/POLD1 and NOTCH4, tumor lymphoid infiltrating cells (TILs), and other novel biomarkers have the potential to develop into new predictors." (PMID 37190201, 2023). "Further exploration found that NOTCH4-Mut tumors had higher tumor mutation burden (TMB) and tumor neoantigen burden (TNB) (P <0.05)." (PMID 35967450, 2022). "Changes in NOTCH4 expression in tumour tissue were significantly associated with patient survival rates." (PMID 35136410, 2022). "We postulate that Notch4 loss likely impacted both tumor and stromal compartments, as supported by the results of the scRNA-seq analysis, which revealed that Notch4 is expressed in both cellular compartments." (PMID 36970723, 2022). "Analysis of the infiltration of immune cells and pathway enrichment analysis also confirmed NOTCH4 mutations increased tumor immunity." (PMID 35967450, 2022). "Integration of the Mouse Mammary Tumour Virus (MMTV) into the Notch1 or Notch4 loci, leading to the expression of an activated form of the respective Notch proteins, had been shown to disrupt mammary gland development and cause tumour development." (PMID 34295896, 2021). "Overall, studies on the association between tumor metastasis and prognosis suggest that VM, Notch4, DLL4, and KAI1/CD82 affect cancer progression." (PMID 30593175, 2018). "Although poor tumor vessel perfusion correlated significantly with delayed tumor onset at early time points after transplantation, our results alone do not provide causal proof that reduced vessel perfusion leads to delayed tumor onset in Notch4−/− mice." (PMID 23601498, 2013). "Host Notch4 deficiency delays tumor onset and decreases initial perfusion, however, the growth of established tumors can ultimately progress in the absence of host Notch4." (PMID 23601498, 2013). "It is also possible that differences in transplantation-associated immune responses contribute to the delayed tumor onset in Notch4−/− hosts." (PMID 23601498, 2013). "Notably, mutations in six genes, including NOTCH4, were detected in the circulating tumour DNA (ctDNA) of NMIBC, which disappeared after an intravenous infusion with ACT, consisting of dendritic cell mixed with cytokines induced killer cells." (PMID 41008920, 2025). "Notch4 polymorphism showed an association with tumor grade (p = 0.03)." (PMID 41027955, 2025). "In addition, in human PDAC, upregulation of Notch4 transcripts have been implicated in both tumor cells and desmoplastic stroma." (PMID 36970723, 2022). "Additionally, the beneficial effects of combining luteolin, a naturally occurring flavonoid, with paclitaxel were mediated through the RSK/YB-1/Notch4 axis, confirming the prospective of increasing tumor susceptibility to apoptosis by Notch4 inhibition." (PMID 34680255, 2021).